LAG3 (lymphocyte activating 3)
Diseases named in the same sentence as LAG3 in open-access papers (continued):
Sharing a sentence is not in itself a finding about the gene and the disease.
breast cancer (131 papers, 2014 to 2026). A primary or metastatic malignant neoplasm involving the breast. "Conversely, LAG-3 expression is associated with a favorable prognosis in esophageal squamous cell carcinoma, resectable gastric cancer, and early breast cancer." (PMID 39751894, 2025). "In breast cancer cohorts, LAG-3 expression is associated with markers of T-cell exhaustion and co-inhibitory molecules such as TIGIT and PD-L1, indicating its potential role in regulating T-cell dysfunction and impairing anti-tumor immune responses." (PMID 41550427, 2025). "The presence of LAG3 + TILs was also associated with longer disease-specific survival in breast cancer patients, as well." (PMID 36765348, 2023). "Based on The Cancer Genome Atlas (TCGA) dataset, we constructed a CD103+LAG3+ TIL-related risk score prognostic model (CLTRP) for patients with breast cancer." (PMID 37488535, 2023). "In breast cancer, elevated levels of LAG3 expression have been positively associated with multiple immune cell infiltrates." (PMID 38115039, 2023). "In gynecological oncology, this combined anti-PD-1 and anti-LAG-3 (REGN3767) antibody approach is under clinical investigation for the treatment of early-stage high-risk HER2− breast cancer patients (NCT01042379)." (PMID 37174080, 2023). "What is more, although LAG3 expression has been associated with more aggressive tumor features in breast cancer, patients with high LAG3 + intraepithelial TILs showed improved survival." (PMID 37311986, 2023). "Other studies found that LAG3 and HLA-E were associated with immunosuppressive effects and tumor immune evasion in breast cancer, gastric cancer, and ovarian cancer, among others." (PMID 37007962, 2023). "For instance, the soluble form of the immune checkpoint molecule lymphocyte activation gene‐3 (LAG‐3), soluble LAG‐3 (sLAG‐3), was highly expressed in breast cancer and associated with poor prognosis." (PMID 35019173, 2022). "By investigating a large intrapatient matched PBT distant MET breast cancer cohort, we have shown that (i) PD-1+/LAG-3+ is strongly associated with a “hot” immune phenotype and (ii) differs between METs and PBTs." (PMID 33413541, 2021). "To characterize the role of LAG3 in breast cancer, we investigated transcriptome data and associated clinical information derived from 2,994 breast cancer patients." (PMID 34267742, 2021). "High LAG3 + expression has been associated with poor prognosis in non-small cell lung cancer, renal cell cancer, hepatocellular cancer, and pancreatic cancer but with favorable prognosis in breast cancer, colon cancer, and esophageal cancer." (PMID 37311986, 2023). "In some tumors like breast cancer, lung adenocarcinoma, and lung squamous carcinoma, the high expression of LAG3 is tightly associated with the increased infiltration of immune cells, including T cells, B cells, cytotoxic lymphocytes, especially that of NK cells and DC cells." (PMID 35111155, 2021). "LAG3 is associated with breast cancer stage, tumor size, tumor grade, and ER/PR/HER2 status." (PMID 35111155, 2021). "The aim of this review is to provide an overview of LAG3 biology under physiological and pathological conditions associated with chronic inflammatory microenvironments, such as that observed in various tumors including breast cancer (BC)." (PMID 31434339, 2019). "LAG3 expression was associated with poor clinicopathological factors and elicited an immune suppressive function, supporting the hypothesis that the expression of LAG3 in breast cancer patients leads to poor survival." (PMID 34267742, 2021). "Our data demonstrate that both DNA and histone modifications are involved in upregulation of PD-1, CTLA-4, TIM-3, and LAG-3 in breast tumor tissue and these epigenetic modifications could be useful as diagnostic/prognostic biomarkers and/or therapeutic targets in breast cancer." (PMID 29983831, 2018).
breast cancer (continued). "Although this axis is targeted by immune checkpoint inhibitors (ICIs), primary resistance occurs in approximately 70–80% of breast cancer patients and is caused by compensatory activation of alternative checkpoints (e.g., TIM-3 and LAG-3)." (PMID 41348261, 2025). "The strong correlation between these pathways and breast cancer patient survival, treatment relapse, and immune inhibitory mediators such as PD-1 and LAG3 highlights their potential as therapeutic targets for preventing and treating metastatic diseases." (PMID 40568095, 2025). "As Icosl depleted, breast cancer didn’t release sIcosl and also significantly enhanced IFNγ expression and inhibited LAG3 presence in both CD4+ and CD8+ T cells." (PMID 40708008, 2025). "As for breast cancer patients with low and high expression of LAG-3, the pCR rates was observed at 64.7% (n=2) vs 35.3% (n=2)." (PMID 38576013, 2024). "Research on LAG-3 in breast cancer has revealed its potential as a prognostic factor and therapeutic target." (PMID 39062758, 2024). "Elevated levels of TIGIT, TIM-3, and LAG-3 are found in locally advanced breast cancer patients with poor prognostic factors following neoadjuvant chemotherapy." (PMID 39717767, 2024). "On the other hand, in breast cancer, LAG-3 expression was positively correlated with the infiltration of cytotoxic and exhausted T cells, as well as with Th1 cells." (PMID 39796650, 2024). "In breast cancer and lung adenocarcinoma, the high expression of LAG3 is closely related to the increase of T cell infiltration." (PMID 38115039, 2023). "A recent study reported that breast cancer-specific survival is longer in patients with LAG-3+ CD8+ iTILs." (PMID 36945923, 2023). "LAG3-positive TILs have been detected in breast cancer patient samples correlating with the HER2-overexpressing subtype." (PMID 36831412, 2023). "We found 361 available breast cancer samples that had been archived between 21st March 2007 and 19th March 2020 and were suitable for PD-1, PD-L1, LAG-3, and TIL evaluation." (PMID 37264298, 2023). "TIM-3, galectin-9, LAG-3 and PD-L2 are expressed in patient-derived breast cancer tissues and are continuously expressed and secreted by different breast cancer-based HTM." (PMID 37174080, 2023). "Previous expression profiling revealed an upregulation of LAG-3 in breast cancer patients, predominantly in the TNBC, HER2+, and luminal A subtypes but not in the luminal B subtypes." (PMID 37174080, 2023). "Nevertheless, dual blockade of LAG-3 and PD-1 is currently being tested for advanced breast cancer (NCT03742349, NCT03005782)." (PMID 37079257, 2023). "In breast cancer, the expression of LAG-3 on TILS was reported in 11% of patients with breast cancer (BC)." (PMID 37509517, 2023). "TCGA database analysis showed that the expression of lag3 in breast cancer tissue was significantly higher than that in normal breast tissue, and with the highest expression in TNBC, especially in TNBC‐IM." (PMID 35894707, 2022). "Among the subgroup of basal-like breast cancers, there was a significant effect of a higher expression of CPS (calculated from LAG-3, CTLA-4 and PD-1) being associated with a longer MFS (p = 0.05, log-rank)." (PMID 36289918, 2022). "In the present retrospective gene-expression analysis, we evaluated the prognostic significance of LAG-3 in 461 patients with early breast cancer." (PMID 36289918, 2022). "This is in line with our findings, showing a significant correlation between LAG-3 and PD-1 mRNA expression (ρ = 0.243; p < 0.001) in a cohort of 461 patients with early breast cancer." (PMID 36289918, 2022). "Soluble LAG3 has been evaluated in different studies, demonstrating a predictive value of prognosis in several solid tumors, including gastric and breast cancer, primary liver cancer, non-small cell lung cancer (NSCLC), and clear cell carcinoma." (PMID 34357118, 2021).
breast cancer (continued). "Measures of soluble LAG-3 in serum have prognostic value, for example, high levels of soluble LAG-3 in some subsets of breast cancer correlate with disease-free, metastasis-free, and overall survival." (PMID 34940257, 2021). "To further characterize the synergistic role of LAG3 in the breast cancer-induced immune response, we evaluated the correlations between LAG3 and other checkpoint members." (PMID 34267742, 2021). "To characterize the association between LAG3 expression and clinical characteristics of breast cancer patients, we dichotomized patients into low- and high-expression groups according to the median cut-off value of LAG3 expression." (PMID 34267742, 2021). "To evaluate the different responses to immunotherapy among the subtypes, we analyzed the mRNA expression of breast cancer immune checkpoint genes, namely PD-1, PD-L1, PD-L2, LAG3, VTCN1, IDO1, and TIM3." (PMID 34277633, 2021). "We found that LAG3 was upregulated in breast cancer tissues compared with normal tissues in TCGA data." (PMID 34267742, 2021). "To further explore the biological functions of LAG3 in breast cancer, we screened 746 and 582 genes that strongly correlated with LAG3 according to Spearman correlation analyses (|R| > 0.4 and P < 0.05) of the TCGA and METABRIC datasets, respectively." (PMID 34267742, 2021). "In particular, higher expression of LAG3 is found in stage I breast cancer, predicting the favorable survival in patients with ER- and ER+ breast cancer, and longer OS and RFS are associated with higher LAG3 expression in TNBC." (PMID 35111155, 2021). "We estimated the landscape of the relationship between LAG3 and 10 types of cell populations of breast cancer." (PMID 34267742, 2021). "To further understand the immune regulatory role of LAG3 in breast cancer, we estimated the absolute abundance of eight immune and two stromal cell populations from transcriptome data through the Microenvironment Cell Populations-counter method." (PMID 34267742, 2021). "In summary, these findings indicate that high expression of LAG3 predicted highly malignant breast cancer." (PMID 34267742, 2021). "To further clarify the role of LAG3 in the immune response to breast cancer, we collected 4,723 immunologically related genes from The Immunology Database and Analysis Portal (ImmPort) database." (PMID 34267742, 2021). "This study is the first integrative analysis, to our knowledge, to molecularly and clinically characterize the landscape of LAG3 expression in breast cancer." (PMID 34267742, 2021). "Nevertheless, PD-1 or LAG-3 expression within distant metastatic breast cancer tissue remains understudied." (PMID 33413541, 2021). "We investigated the correlation pattern between LAG3 and immune modulators in pancancer, particularly the synergistic role of LAG3 with other immune checkpoint members in breast cancer." (PMID 34267742, 2021). "Multiple ICRs, including PD-1, CTLA-4, TIM-3, and LAG-3, were found to be upregulated in breast cancer tissues as compared to normal breast tissue." (PMID 33823818, 2021). "LAG had the strongest correlation with T cells, indicating the important role of LAG3 in T cell-induced immune functions in breast cancer." (PMID 34267742, 2021). "In vitro and in animal models, we have seen that blocking PD-1/PD-L1 and LAG3 pathways at the same time is better than single blocking, which provides new space for immunotherapy for breast cancer." (PMID 34631507, 2021). "We found that LAG3 was upregulated in breast cancer tissue, particularly enriched in the basal, HER2-positive, and LumA subtypes, as well as in patients with higher tumor grades." (PMID 34267742, 2021). "In fact, the PD-1/PD-L1 axis plays an important role in tumor immune response, in both human and feline breast cancers, and is up-regulated together with LAG-3 in human breast cancer." (PMID 34771722, 2021). "Together, these results indicate that high expression of LAG3 predicts a highly malignant breast cancer." (PMID 34267742, 2021).
breast cancer (continued). "Our study emphasizes the careful assessment of the immune phenotype and PD-1/LAG-3 expression in metastatic breast cancer tissue to overcome intrapatient tumor heterogeneity." (PMID 33413541, 2021). "Yet, in contrast, several studies have found that high LAG-3 was correlated with better survival in patients with gastric carcinoma and breast carcinoma." (PMID 34454491, 2021). "Conversely, several studies indicate that LAG-3 expression is related to a better survival for gastric cancer and breast cancer patients." (PMID 34454491, 2021). "When evaluating the different populations in tumors with high expression of LAG3, we observed a positive correlation with the presence of neutrophils in the entire breast cancer subgroup and in the basal-like subtype (part." (PMID 32796628, 2020). "Previously, we showed that the co-blockade of PD-1 and PD-L1 upregulated the surface expression of CTLA-4, TIM-3, and LAG-3 on CD4+ T cell subsets by using a co-culture system with human breast cancer cell lines." (PMID 32616706, 2020). "This prognostic relevance is in line with previous studies investigating LAG3 in other tumor types, even though studies with breast cancer came to divergent results." (PMID 32232506, 2020). "Then, we validated the protein expression of immune checkpoint molecules (VISTA, PD-1, PD-L1, TIGIT, TIM3, and LAG3) in 324 human breast cancer samples by immunohistochemistry and quantitative immunofluorescence (QIF) approaches." (PMID 33250890, 2020). "Several researches have shown that LAG-3 expression was related to the metastasis and prognosis of various cancers such as breast cancer, lung cancer, and ovarian cancer." (PMID 31781309, 2019). "We briefly discuss its role in infection, autoimmune disease and cancer, with a more detailed analysis of current data on LAG3 expression in breast cancer." (PMID 31434339, 2019). "We found that the co-expression of TIM-3/LAG-3 was upregulated in FoxP3+Helios+ Tregs in the presence of breast cancer cells." (PMID 31614877, 2019). "LAG-3 has been shown to suppress immune responses in several tumors, including Hodgkin's lymphoma, gastric cancer, breast cancer, and other solid tumors." (PMID 31681269, 2019). "Currently, immune checkpoint therapies by targeting CTLA-4, PD-1, or lymphocyte activation gene-3 (LAG-3) pathways for breast cancer are still in clinical trial." (PMID 28085094, 2017). "Importantly, high frequencies of PD-1/PD-L1+ tumors in non-small-cell lung cancer and breast cancer often show co-infiltration with LAG-3+ TILs." (PMID 41300994, 2025). "Furthermore, our analysis shows enrichment of potential immune checkpoint targets in high-proliferation breast cancer, including PD-1, Lag3, IDO, and PD-L1 elevation." (PMID 39808504, 2025). "A study on breast cancer patients with liver or brain metastases who responded poorly to anti-PD-1 therapy found that targeting LAG3 in combination with other co-inhibitory receptors, such as TIGIT, represents a potential therapeutic strategy for tumors with low PD-1 expression." (PMID 40411616, 2025). "However, the impact of LAG-3 expression on metastasis-free survival in early breast cancer is less clear, with some studies suggesting a favorable outcome and others finding no significant impact." (PMID 39062758, 2024). "However, single-cell transcriptomic sequencing of breast cancer cells that metastasized to the liver and brain showed that the expression of the immunoreceptor inhibitory checkpoint genes, LAG3 and TIGIT, in T cells was higher than that of PDCD1 (PD-1)." (PMID 38462658, 2024). "Therefore, a series of dual blockade approaches targeting LAG-3 and PD-1 is currently undergoing clinical evaluation as a potential treatment option for advanced breast cancer (NCT03742349 and NCT03005782), and double antibodies are under evaluation." (PMID 39430759, 2024).
breast cancer (continued). "Studies have shown that LAG-3 expression is associated with improved survival in HR negative breast cancer, particularly when co-expressed with CD8+ TILs." (PMID 39062758, 2024). "Our results showed that T cells from breast cancer patients have a reduced ability to respond to stimulation in-vitro and an increased expression of senescence and exhaustion-associated markers, such as TIM-3, LAG3, and CD57." (PMID 36763585, 2023). "Finally, a sizable proportion of breast cancers co-express PD-L1 and LAG-3, which will make them appropriate targets for future combined ICIs." (PMID 37264298, 2023). "LAG3 mRNA expression was higher in breast cancer (P < 0.001), esophageal cancer (P < 0.001), head and neck cancer (P < 0.001), kidney clear cell carcinoma (P < 0.001), lung adenocarcinoma (P < 0.001), and lung squamous cell carcinoma (P < 0.001) than in normal tissues." (PMID 38062416, 2023). "Multiplex immunohistochemistry showed the presence of CD103+LAG3+ B cells in breast cancer." (PMID 37488535, 2023). "In this study, we aimed to determine the expression status of PD-1, PD-L1, LAG-3, and the densities of TILs of breast cancer pathologic samples from Iranian women for the first time and further investigate their possible associations with the clinicopathologic features of cases." (PMID 37264298, 2023). "Interestingly, low LAG3 + expression became an independent predictor of favorable prognosis in breast cancers that were treated with neoadjuvant chemotherapy." (PMID 37311986, 2023). "In addition, LAG-3 expression was closely related to an enhanced malignancy of breast cancer and poor clinico-pathological factors." (PMID 37174080, 2023). "LAG-3+ intra-epithelial tumor infiltrating lymphocytes were found in 11% of cases of breast cancer." (PMID 36077354, 2022). "However, breast cancer patients with LAG-3+ iTILs had significantly improved breast cancer-specific survival." (PMID 36077354, 2022). "The results that the co-expression predict diverse prognosis can be attributed to the interactions between LAG3 and other molecules are different; the discrepancy in breast cancer can be attributed to the various immune microenvironment of breast cancer subtypes." (PMID 35111155, 2021). "Furthermore, due to our interest in LAG-3 and PD-1 expression in metastatic tissue, our cohort is biased for patients with advanced metastatic disease thus differing from an average breast cancer cohort." (PMID 33413541, 2021). "Previous studies document the inhibitory role of T cell activation, although it is unclear whether LAG3 plays the same role in breast cancer and whether LAG3 influences other immune cells." (PMID 34267742, 2021). "To further explore the association of LAG3 expression and the malignancy of breast cancer, we compared the expression of LAG3 between the TNBC and None-TNBC groups." (PMID 34267742, 2021). "In contrast to the previous results, neither the immune phenotype nor PD-1/LAG-3 expression was associated to the molecular breast cancer subtype possibly due to the overall small number of patients in our cohort." (PMID 33413541, 2021). "In the present study, we systematically analyzed the expression of LAG3 in breast cancer." (PMID 34267742, 2021). "However, the coexpression and effects of LAG3 and PD-1 on T cells in breast cancer patients are unclear." (PMID 34267742, 2021). "To address this knowledge gap, we assessed the CD8+ T cell immune phenotype as well as PD-1 and LAG-3 expression in primary tumors (PBTs) with intrapatient matched distant metastases (METs) in a retrospective cohort of 95 breast cancer patients by using immunohistochemistry on whole sections." (PMID 33413541, 2021). "The impacts of LAG3 on immune cell populations and coregulation of immune responses in breast cancer remain largely unknown." (PMID 34267742, 2021). "In breast cancer, the predictive value of LAG-3 expression remains still unclear." (PMID 33413541, 2021).